S100A4 (S100 calcium binding protein A4)
Diseases named in the same sentence as S100A4 in open-access papers (continued):
Sharing a sentence is not in itself a finding about the gene and the disease.
breast carcinoma (continued). "Assessment of S100A4 expression in brain metastatic and non-metastatic primary breast carcinomas." (PMID 27100728, 2016). "This was followed by reports that transfection of either human or rat S100A4 DNA can induce a metastatic phenotype upon nonmetastatic rat mammary tumour cells, whereas inhibition of S100A4 expression in metastatic cells can revert cells to a less metastatic phenotype." (PMID 15900299, 2005). "In addition, the role of S100A4 in bone metastasis of breast cancers has not yet been reported." (PMID 31667000, 2019). "Of particular note, TuNEPs derived from PC9 cells lacked HMG family proteins and S100a4, which were identified in TuNEPs from human MDA-MB-231 LM3 and mouse 4T1 breast cancer cells, and were critical for their roles in metastatic outgrowth." (PMID 40751052, 2025). "Although S100A1 does not seem to be directly involved in breast cancer signalling, it was shown that S100A1 reduces the activity of intracellular S100A4." (PMID 32722137, 2020). "For example, in breast cancer, the ganciclovir-mediated depletion of proliferating FSP1/S100A4+ stromal cells did not impact primary tumor growth, but it resulted in suppressed metastasis." (PMID 29686035, 2018). "S100A4-positive cells, which did not express the CD45 immune cell marker, were also detected in the metastatic microenvironment of human breast cancers." (PMID 22509805, 2012). "We have previously identified the EF-hand (helix-turn-helix structural domain) calcium-binding protein S100A4 (metastasin) as a relaxin target in oestrogen-independent, ERα-negative, highly invasive MDA-MB-231 human breast cancer cells." (PMID 18718015, 2008). "The differential impact of staining for AGR2 on prognosis in ERα-positive and ERα-negative patients is in contrast to the adverse effect of staining for S100A4 and OPN on the survival of patients with breast cancer which are apparent in both ERα-positive and ERα-negative subgroups." (PMID 16598187, 2006). "We demonstrated that, in breast cancer cells, VEGF mRNA and protein expressions were upregulated by Osx, indicating that Osx is involved in regulation of breast cancer angiogenesis, and we found that Osx promotes breast cancer angiogenesis through upregulation of S100A4 and VEGF (data not shown)." (PMID 30631043, 2019).
colorectal cancer (64 papers, 2004 to 2025). A primary or metastatic malignant neoplasm that affects the colon or rectum. "It is important in the initiation of colorectal cancer and SATB1 expression in colorectal cancer is associated with the expression of S100A4, MMP2, NF-kB, PCNA, cyclin D1 and β-catenin." (PMID 33356851, 2020). "Several S100 family members seem to be promising biomarkers, for example, high expression of S100A4 is associated with poor survival and increased aggressiveness when studying colorectal carcinoma (CRC) patients." (PMID 32722137, 2020). "High S100A4 expression levels are associated with aggressive tumor growth, metastases, and poor prognosis in colorectal cancers." (PMID 30111999, 2018). "In colorectal cancer, S100A4 causes increased cell motility, which is mediated via the receptor for advanced glycation endproducts (RAGE) and downstream (mitogen‐activated protein kinase) (MAPK/ERK) signalling." (PMID 26928771, 2016). "A similar association between elevated S100A4 expression and lymphovascular invasion has previously been demonstrated in colorectal carcinoma." (PMID 27127879, 2016). "We have recently demonstrated the diagnostic and prognostic value of circulating S100A4 transcripts in colorectal cancer and in gastric cancer patients." (PMID 23166620, 2012). "This was caused by reduced S100A4 mRNA expression in tumors and metastases of human colorectal cancer xenografted mice." (PMID 22878175, 2012). "S100A4 has previously been linked to enhanced tumor migration and formation of metastasis of colorectal cancer." (PMID 22878175, 2012). "Moreover, we have recently demonstrated nuclear localization of S100A4, and an association between nuclear expression and tumor stage in colorectal cancer, indicating other, yet undiscovered, functions of S100A4." (PMID 15318945, 2004). "S100A4 can activate NF-κB signaling and the Wnt–β-catenin pathway to promote tumorigenesis and metastasis in colorectal cancer." (PMID 41134679, 2025). "We confidently identified known prognostic biomarkers for colorectal cancer, such as S100A4, LGALS1, and FABP5." (PMID 38580967, 2024). "Two colorectal cancer cell lines with different intrinsic S100A4 and MACC1 gene expression levels were used: HCT116 cells with moderate expression levels of S100A4 and MACC1 and SW620 with high expression levels of S100A4 and MACC1." (PMID 36674695, 2023). "The high potential of S100A4 as a therapeutic target was shown in several studies for colorectal cancer." (PMID 35326507, 2022). "The use of new therapeutic interventions or screening of pharmacologically active compounds is strongly recommended to reduce the expression of S100A4 in colorectal cancer." (PMID 36499426, 2022). "In a study of colorectal cancer, adenovirus-mediated S100A4 overexpression enhanced the viability and migration of colorectal cancer cells; these effects of S100A4 were reduced by treatment with the specific PI3K/Akt signaling inhibitor LY294002." (PMID 35214097, 2022). "Overexpression of S100A4 has been reported in various malignancies, including pancreatic cancer, gastric cancer, colorectal cancer, esophageal cancer, and NSCLC." (PMID 32696952, 2020). "PI3K/Akt/mTOR/p70S6K, an important signaling pathway involved in cancer progression and metastasis, causes S100A4-promoted cell viability and migration, and promotes the VEGF secretion level through downregulation of E-cadherin in colorectal cancer cells." (PMID 30871059, 2019). "Bioinformatics analyses indicated that HMGA2-overexpressing colorectal cancers shift their dependency from HMGA2 to S100A4 that predicts a poor disease-free survival in colorectal cancer patients." (PMID 31581665, 2019). "Specifically, the connectivity scores of niclosamide (−92.86) and S100A4 knockdown (−99.03) were similar in HT29 human colorectal cells, further supporting the potency of niclosamide to inhibit S100A4 in colorectal cancer." (PMID 31581665, 2019).
colorectal cancer (continued). "S100A4 is a well-known metastasis-inducing gene in colorectal cancer and S100A4 inhibition for therapeutic intervention is suggested." (PMID 31581665, 2019). "Previous studies showed that extracellular S100A4 induces NF-κB activation and mediates cancer progression in colorectal cancer, thyroid cancer, malignant melanoma, and prostate cancer." (PMID 30041429, 2018). "Interaction of S100A4-AGER mediates S100A4-induced cell motility in colorectal cancer and thyroid cancer." (PMID 29298878, 2018). "Logically, knock down of S100A4 resulted in decreased metastasis formation in a xenografted mouse model of colorectal cancer." (PMID 26928771, 2016). "S100A4 expression was analyzed by immunohistochemistry in primary colorectal carcinomas from a consecutively collected, population‐representative cohort and a randomized phase III study on adjuvant 5‐fluorouracil/levamisole." (PMID 27273130, 2016). "Here we demonstrate the RAGE-dependent increase in migratory and invasive capabilities of colorectal cancer cells via binding to extracellular S100A4." (PMID 24952599, 2014). "Accumulated evidence has indicated a correlation between S100A4 expression and colorectal cancer (CRC) progression." (PMID 24188373, 2013). "In this study, we demonstrate the reduction of S100A4 induced in vivo metastasis formation in xenografted colorectal cancer tumors by systemic application of plasmids expressing S100A4-specific shRNA, via tail vein injection." (PMID 22878175, 2012). "Overexpression of S100A4 in colorectal cancer tissue correlates with higher metastasis formation and is associated with a decrease of the patients’ survival rate." (PMID 22878175, 2012). "In this study, we first examined the expression of S100A4 in six colorectal cancer cell lines with various invasive potentials at the mRNA level by real-time PCR and at the protein level by Western blotting." (PMID 22200787, 2012). "In the present study, we used shRNA expression plasmids to inhibit S100A4 expression in the colorectal cancer cell lines HCT116, SW620 and DLD-1." (PMID 22878175, 2012). "We verified the reduction of cellular motility after S100A4 knock-down in the colorectal cancer cell lines SW620 and DLD-1." (PMID 22878175, 2012). "S100A4 protein, a member of the S100 superfamily of calcium-binding proteins, is frequently observed in various types of human cancers, including colorectal cancer (CRC)." (PMID 22200787, 2012). "In summary, we show for the first time the intratumoral knock-down of S100A4 via systemic application of S100A4-shRNA plasmid DNA, which restricts metastasis formation in a xenografted mouse model of colorectal cancer." (PMID 22878175, 2012). "In our study, the stable knock-down of S100A4 in the colorectal cancer cell lines HCT116, SW620, and DLD-1, by plasmid based shRNA expression, did not result in reduced cellular growth in vitro." (PMID 22878175, 2012). "The data indicate that RNAi effectively suppresses S100A4 expression in SW620 colorectal cancer cells." (PMID 22200787, 2012). "S100A4 expression levels correlate with the formation of human colorectal cancer metastases and shorter patients’ survival." (PMID 22878175, 2012). "The level of S100A4 expression among the six colorectal cancer cell lines roughly coincided with their invasiveness, which was consistent with our previous conclusion that increased expression of S100A4 correlated with increased invasiveness in tumor tissues." (PMID 22200787, 2012). "We first examined the expression of S100A4 by quantitative real-time PCR in six colorectal cancer cell lines." (PMID 22200787, 2012). "Our previous study found that the overexpression of S100A4 existed more frequently in colorectal cancer patients with advanced stage, lymph node metastasis and was associated with poor prognosis." (PMID 22200787, 2012). "Our results showed a clear decrease in the metastatic potential of colorectal cancer cells, when stably transfected with S100A4-shRNA expression plasmids." (PMID 22878175, 2012).
colorectal cancer (continued). "Very recently, it has been reported that niclosamide was able to inhibit Wnt/β-catenin signaling in colorectal cancer cells, inhibited colorectal cancer growth and S100A4-mediated metastatic colorectal cancer." (PMID 22195040, 2011). "Using this strategy, two excised spots from SW620 whole cell lysate, three from a primary colorectal carcinoma biopsy and two from in-house produced recombinant S100A4 were confirmed to contain human S100A4." (PMID 18554396, 2008). "The finding that human S100A4 isolated from primary colorectal carcinomas, cell lines and normal cells resulted in similar patterns is remarkable and suggests that the observed 2D-PAGE distribution is a general phenomenon." (PMID 18554396, 2008). "Niclosamide inhibited Wnt/b-catenin pathway activation, decreased downstream b-catenin signaling, decreased S100A4 mRNA and protein expression, and had antiproliferative effects in colorectal cancer HCT-116 cells, human hepatic cancer cell lines (HepG2), and mouse liver metastasis." (PMID 39191850, 2024). "Angiogenesis and prognostic roles of S100A4 in colorectal cancer have been investigated." (PMID 38729966, 2024). "S100A4 plays an important role in immune system regulation, particularly in the modulation of inflammatory responses across diverse diseases, including colorectal cancer, amyotrophic lateral sclerosis (ALS), and asthma." (PMID 37628889, 2023). "Thus, we demonstrated high prognostic significance of angiogenesis-associated factors S100A4, SPP1 and SPARC that are produced by TAMs in colorectal cancer." (PMID 36895491, 2023). "In addition, applying HEART on two subpopulations of megakaryocytes, we found several potential cancer biomarkers (CTTN, S100A4, S100A6, UBA52, FAU, and VIM, etc.)associated with colorectal cancer progression and metastasis in literature." (PMID 36523772, 2022). "Finally, S100A4 has been shown to be targeted by miR-296 in both ovarian and colorectal cancer cells." (PMID 35317077, 2022). "S100A4 may also be epigenetically regulated in colorectal cancer by tumor-suppressor miRs, miR-505c-5p, and miR-520c-3p, which promote S100A4-mediated migration and invasion of cancer cells." (PMID 34209679, 2021). "The mRNA for S100A4 and S100A4 proteins has a prognostic significance in colorectal cancer." (PMID 33466593, 2021). "Downregulation of miR-520c induced S100A4 expression in colorectal cancer." (PMID 34485305, 2021). "Interestingly, inhibition of S100A4 cannot fully explain the sensitizing effect of niclosamide on HMGA2-overexpressing colorectal cancer cells, suggesting that additional mechanisms are involved." (PMID 31581665, 2019). "The S100A4 protein may be a beneficial marker to predict the carcinogenesis, tumor progression, and prognosis in colorectal cancers." (PMID 30111999, 2018). "The metastasis‐promoting protein S100A4 predicts poor outcome in colorectal cancer, but whether it could be used to guide clinical decision making remains to be resolved." (PMID 27273130, 2016). "In summary, interaction of S100A4-RAGE mediates S100A4-induced colorectal cancer cell motility." (PMID 24952599, 2014). "S100A4 is a prognostic biomarker and inducer for colorectal cancer metastasis." (PMID 24952599, 2014). "S100A4 may be a useful marker to predict development, progression, and prognosis of colorectal cancer." (PMID 24188373, 2013). "In the present study, we used gene specific shRNA to inhibit S100A4 expression in the colorectal cancer cell lines HCT116, SW620, and DLD-1, resulting in reduced cell motility in vitro and, for HCT116, reduced metastasis formation after xenograft transplantation in vivo." (PMID 22878175, 2012). "CDH11 exhibited lower expression after S100A4 silencing in colorectal cancer cells, suggesting that it may correlate with S100A4." (PMID 22200787, 2012).
colorectal cancer (continued). "The combination of the two metastasis-inducing genes, MACC1 - a key regulator of the HGF/Met signaling pathway, with S100A4– a transcriptional target gene of the Wnt/β-catenin signaling pathway, improves survival prediction for newly diagnosed colorectal cancer patients." (PMID 23166620, 2012). "For the first time, we performed systemic, hydrodynamics-based delivery of S100A4-shRNA expression plasmids thereby decreasing the S100A4 expression in the tumor tissue of xenografted mice for colorectal cancer, which led to reduced metastasis formation in vivo." (PMID 22878175, 2012). "Furthermore, S100A4 has been shown to be a prognostic biomarker when determined in colorectal cancer tissues by qRT-PCR and immunohistochemistry." (PMID 23166620, 2012). "Recently, many studies have shown that S100A4 is an important factor relevant to progression and prognosis in various human cancers, such as thyroid tumors, breast, pancreatic, lung, gastric and colorectal cancers." (PMID 22200787, 2012). "Therefore, we thought that S100A4 might serve as a potential therapeutic target for HMGA2-overexpressing colorectal cancer." (PMID 31581665, 2019). "Therefore, we speculated that S100A4 inhibition by niclosamide may exhibit therapeutic benefit for HMGA2-overexpressing colorectal cancer." (PMID 31581665, 2019). "Thus, therapeutic approaches targeting RAGE or intervening in S100A4-RAGE-dependent signaling early in tumor progression might represent alternative strategies restricting S100A4-induced colorectal cancer metastasis." (PMID 24952599, 2014). "S100A4 expressing CAFs secrete VEGF-A and Tenascin-C to promote metastatic colonization of the lung and liver in mouse breast and colorectal cancer models." (PMID 40078995, 2025). "Therefore, inhibition of S100A4 might be a novel approach to the treatment of colorectal cancer." (PMID 33466593, 2021). "NFAT5, a transcription regulator, regulates the Wnt/β-catenin signaling pathway and also influences the S100A4 gene, which is a direct transcriptional target of the Wnt/β-catenin/TCF-mediated signaling pathway in colorectal cancer." (PMID 34830168, 2021). "As an important paralog of S100A4, S100A2 is reported to be abnormally highly expressed in various tumors, such as colorectal cancer and lung cancer." (PMID 34530774, 2021). "A repurposing S100A4 inhibitor, niclosamide, was found to reverse the HMGA2-driven gene signature both in colorectal cancer cell lines and patients’ tissues." (PMID 31581665, 2019). "Thus, a personalized RNA interference approach to reduce the S100A4 expression in those patients with high S100A4 expressing primary tumors might serve as an alternative or addition to adjuvant chemotherapeutic protocols for prevention of metastasis formation in colorectal cancer." (PMID 22878175, 2012). "To demonstrate the role of S100A4 in tumor development and progression, we silenced the expression of S100A4 using RNAi in the colorectal cancer cell line SW620 with highly invasive potential and S100A4 high expression." (PMID 22200787, 2012). "Besides S100A4 and S100P, we confirmed that the expression of S100A11 is enhanced in colorectal cancer, so the high expression of S100A11 in colorectal cancer leads us to a prediction of the cancer progression state." (PMID 38842658, 2024). "Consequently, we supposed that a series of genes, CTTN, S100A4, S100A6, etc., were potential colorectal cancer metastasis biomarkers." (PMID 36523772, 2022). "Furthermore, we applied HEART to a single-cell dataset of a colorectal cancer patient and identified several potentially metastasis-related biomarkers, CTTN, S100A4, S100A6, etc." (PMID 36523772, 2022). "This could be explained by the fact that RAGE mediated S100A4-induced cell motility via MAPK/ERK signaling pathway and promoted human colorectal cancer metastasis." (PMID 35610613, 2022).